CCND3 (cyclin D3)
Diseases named in the same sentence as CCND3 in open-access papers (continued):
Sharing a sentence is not in itself a finding about the gene and the disease.
metastatic disease (3 papers, 2020 to 2024). "There were rare amplifications of the D-cyclin genes (CCND1, CCND2, and CCND3); interestingly, each of these events occurred in tumors from patients with metastatic disease." (PMID 32198354, 2020).
Obesity (3 papers, 2010 to 2024). Accumulation of substantial excess body fat. "When the obesity causal genes were overlapped with the fasted and fed networks, 7 genes (ADA, BBS5, CBL, CCND3, FASN, FTO and SCARB1) overlapped with PER1's downstream genes in the fed network (Fisher's Exact Test p-value = 0.037)." (PMID 20168994, 2010).
oral squamous cell carcinoma (3 papers, 2006 to 2021). "Upregulation of CCND1 and CCND3 genes was associated with cisplatin resistance in human oral squamous cell carcinoma cell lines." (PMID 33923996, 2021). "Furthermore, our preliminary results from 50 oral squamous cell carcinoma samples showed that the inverse expression pattern of CCND1 and CCND3 correlates with cisplatin sensitivity." (PMID 16978399, 2006).
rhabdomyosarcoma (3 papers, 2014 to 2025). A rare aggressive malignant mesenchymal neoplasm arising from skeletal muscle. "AZD8055 and MK2206 decreased Cyclin D2, D3 and E in Rh30 cells whereas rapamycin also decreased both Cyclin D2 and D3 but not Cyclin E (Cyclin D2 and Cyclin D3 are the major G1 phase cyclins in rhabdomyosarcoma, Shen and Houghton, unpublished)." (PMID 28484242, 2017).
viral infection (3 papers, 2012 to 2018). "Other members of the network also reappeared in the gene set enrichment analysis as members of pathways associated with viral infections (DDX58, IFIT1, IRF1, MX1, STAT1) or viral carcinogenesis and cell cycle (CCND1, CCND3, CCNE1, CDC20, E2F2, RANBP1)." (PMID 30042828, 2018). "To address the reduction of cyclin D3 from the nucleus upon virus infection, we fractionated both control and infected cells into cytosol and nuclear material to measure cyclin D3 levels." (PMID 28130444, 2017). "It is worth noting that a unique role for cyclin D3 in promoting virus infection has also been observed in promoting herpes simplex virus reactivation." (PMID 22319441, 2012). "The effect of M2 protein on cyclin D3 relocalization was recapitulated in analogous experiments using A549 cells expressing M2 protein alone, which resulted in the apparent reduction of cyclin D3 from the nucleus, similar to the phenotype induced by viral infection." (PMID 28130444, 2017). "Interestingly, upon virus infection, a much weaker cyclin D3 signal was observed in the nuclei of infected cells compared with control cells, as revealed by M2 staining." (PMID 28130444, 2017). "Although viral infection also resulted in cyclin D1, CDK4, and CDK6 down-regulation on protein level, the level of down-regulation is not as robust as that of cyclin D3, and their protein levels could not be rescued by protease and calpain inhibitor when compared with cyclin D3." (PMID 28130444, 2017).
cholangiocarcinoma (2 papers, 2022 to 2023). A carcinoma that arises from the intrahepatic biliary tree (intrahepatic cholangiocarcinoma) or from the junction, or adjacent to the junction, of the right and left hepatic ducts (hilar cholangiocarcinoma). "Induction of G0/G1 cell cycle arrest in cholangiocarcinoma cells by vitamin D analogues is mediated by upregulation of p27 and downregulation of CDK4, CDK6, and cyclin D3." (PMID 37561808, 2023).
chronic lymphocytic leukaemia (2 papers, 2021 to 2023). "Increased expression of CCND3 has also been observed in chronic lymphocytic leukaemia (CLL) cells, with RNA sequencing identifying a 38-fold increase in CCND3 in NOTCH1-mutated cells compared to NOTCH1 non-mutated cells." (PMID 37510349, 2023). "In chronic lymphocytic leukemia (CLL), ZNF224 acts as a direct transcriptional activator of the cyclin D3 gene, thus exerting an important role in cell growth and drug resistance." (PMID 34684876, 2021).
diabetes (2 papers, 2020 to 2021). "In adult mouse beta cells, we did not observe changes in replication due to either Cyclin D3 or the CDK11 hemideficiency, which suggests that the protection against diabetes is not related to proliferation." (PMID 33664748, 2021).
endometrial carcinoma (2 papers, 2000 to 2022). A malignant tumor arising from the epithelium that lines the cavity of the uterine body. "We analysed p16 gene alteration and p16, cyclin-dependent kinase 4 (CDK4), CDK6, cyclin D1, cyclin D2, cyclin D3 and retinoblastoma protein (pRb) expression in ten normal endometriums (PE), 18 endometrial hyperplasias (EH) and 35 endometrial cancers (EC)." (PMID 10682682, 2000).
follicular lymphoma (2 papers, 2021 to 2022). Follicular lymphoma is a form of non-Hodgkin lymphoma characterized by a proliferation of B cells whose nodular structure of follicular architecture is preserved. "The relationship between clinical variables as well as BCL2 or CCND3 mutation status and follicular lymphoma survival." (PMID 35795062, 2022).
Influenza Infection (2 papers, 2017 to 2022). "Our results indicate that cyclin D3 functions beyond its role in cell cycle in the context of influenza infection." (PMID 28130444, 2017). "The role of cyclin D3 in the context of influenza infection has not been described previously." (PMID 28130444, 2017).
invasive breast carcinoma (2 papers, 2008 to 2018). A carcinoma that infiltrates the breast parenchyma. "Overexpression of cyclin D3 has been reported in invasive breast cancer and represents an independent prognostic marker." (PMID 29963272, 2018).
meningioma (2 papers, 2022 to 2024). A generally slow growing tumor attached to the dura mater. "CDK4 and cyclin D3 drive meningioma cells into the S phase and enhance cell proliferation and migration." (PMID 38398158, 2024). "This interaction promotes the transcription of cell cycle genes CDK4 and cyclin D3 through the activation of the NF-κB pathway, thereby enhancing the proliferation of meningioma cells." (PMID 38398158, 2024). "Transcriptome sequencing data analysis revealed that RACK1 knockdown significantly downregulated the cell cycle pathway in meningioma cells, with CDK4 and cyclin D3 being the most affected." (PMID 38398158, 2024).
steatosis (2 papers, 2020 to 2024). Increased lipid within the cytoplasm of cells. "Their hits elucidated the cyclin D3-cyclin-dependent kinase 2–4 (CDK2-4)/CCAAT-enhancer-binding proteins (C/EBP)/diacylglycerol acyltransferase 2 (DGAT2) pathway as contributing to endoplasmic reticulum stress-induced steatosis." (PMID 39000384, 2024).
T cell lymphomas (2 papers, 2011 to 2022). "Interestingly, cyclin D3 and CDK4 are overexpressed in NOTCH-dependent T cell lymphomas, indicating that cell-cycle inhibitors and GSI should be used together to treat T cell lymphomas." (PMID 35681778, 2022).
T-cell leukemia (2 papers, 2019 to 2022). A malignant disease of the T-lymphocytes in the bone marrow, thymus, and/or blood. "However, the expression of cyclin D2 and cyclin D3 is rare compared with the universal expression of cyclin D1 in most cancers, and that cyclin D3 plays a unique role mainly in T-cell leukemia." (PMID 36059670, 2022).
adenoma (1 paper, 2015). A neoplasm arising from the epithelium. "Our study is the first that combines dimension, a nuclear marker (cyclin D3), and a nuclear-cytoplasmic marker (Gal-3) to differentiate oncocytic carcinomas and adenomas." (PMID 26604924, 2015).
AIDS (1 paper, 2022). A syndrome resulting from the acquired deficiency of cellular immunity caused by the human immunodeficiency virus (HIV). "Moreover, CCND3 mutation promotes the acquisition of clonal lymphoproliferative phenotypes of B cells, which could potentially act as a pathogenic mechanism of DLBCL with AIDs." (PMID 35237512, 2022).
B-cell lymphoblastic leukaemia (1 paper, 2023). "A role of CCND3 in B-cell lymphoblastic leukaemia (B-ALL) was also described, with CCND3 being found to be indispensable for the growth and survival of B-ALL cells irrespective of the underlying driver mutation." (PMID 37510349, 2023).
B-cell neoplasm (1 paper, 2023). A group of heterogeneous lymphoid tumors generally expressing one or more B-cell antigens or representing malignant transformations of B-lymphocytes. "However, the expression of CCND2 or CCND3 without the presence of a detectable translocation, particularly in SOX11-negative tumours, should not be considered as evidence of MCL since B cell neoplasms express variable levels of CCND2 or CCND3 without translocations of these genes." (PMID 36454275, 2023).
clear cell renal cell carcinoma (1 paper, 2023). "In F107 case, interestingly, amplification of VEGFA and CCND3 on chromosome 6 was observed, which may lead to the formation of clear cell renal cell carcinoma." (PMID 37182269, 2023).
dopaminergic neuroblastoma (1 paper, 2022). A neuroblastoma associated with increased dopamine excretion. "The sulfated polysaccharide isolated from sea cucumber Stichopus japonicus on the 6-hydroxydopamine-induced apoptosis in SH-SY5Y cells (a human dopaminergic neuroblastoma cell line) significantly elevated protein levers of Cyclin D3." (PMID 35215436, 2022).
embryonal carcinoma (1 paper, 2005). A non-seminomatous malignant germ cell tumor characterized by the presence of large germ cells with abundant cytoplasm resembling epithelial cells, geographic necrosis, high mitotic activity, and pseudoglandular and pseudopapillary structures formation. "In addition, in the embryonal carcinoma cell line NTERA-2, cyclin E-dependent CDK2 activity, but not cyclin D3-dependent CDK4 activity, was suppressed as a result of hexamethylene-bisacetamide-induced differentiation." (PMID 16012517, 2005).
erythroleukemia (1 paper, 2024). Acute erythroid leukemia characterised by the presence of at least 50% erythroid precursors and at least 20% myeloblasts in the bone marrow. "For example, PLCB1 can significantly increase the expression levels of Cyclin D3 and the percentage of S phase cells in the K562 human erythroleukemia cell line." (PMID 38731807, 2024).
HIV-1 infection (1 paper, 2016). The type species of lentivirus and the etiologic agent of acquired immunodeficiency syndrome (AIDS). "Accordingly, knockdown of cyclin D2 and cyclin D3 resulted in opposite effects depending on the macrophage type, in terms of susceptibility to HIV-1 infection: cyclin D2 restricts infection in non-cycling GM-CSF macrophages and cyclin D3 enables infection in proliferating M-CSF macrophages." (PMID 27541004, 2016).
hyperphosphatemia (1 paper, 2011). Abnormally high level of phosphate in the blood. "While simulated hyperphosphatemia led to a decrease in the level of cyclin D3, simulated hypophosphatemia led to an increase in the level of CDK2 in HUVECs." (PMID 21858050, 2011).
hyperthyroidism (1 paper, 2024). Overactivity of the thyroid gland resulting in overproduction of thyroid hormone and increased metabolic rate. "However, according to the authors’ knowledge, the influence of TSH on cyclin D3 in erythropoiesis in hyperthyroidism has not been investigated, either in humans or animals." (PMID 39518858, 2024).
lymph node metastasis (1 paper, 2025). "Another analysis using an RNA sequencing dataset (GN20211018003) derived from 20 LUAD specimens revealed that CCND3 expression was higher in the 4 LUAD cases without lymph node metastasis but lower in the 16 LUAD cases with lymphatic spread." (PMID 39781469, 2025).
malaria (1 paper, 2026). Malaria is a serious and sometimes fatal disease caused by a parasite that commonly infects a certain type of mosquito which feeds on humans. "Our results suggest that a reduction in CCND3 in erythroblasts constitutes a mechanism of resistance to malaria, and could enable therapeutic interventions." (PMID 41708853, 2026).
mesothelioma (1 paper, 2014). A usually malignant and aggressive neoplasm of the mesothelium which is often associated with exposure to asbestos. "Cyclins D1, D2, D3, and E were detected in all mesothelioma cell lines, and cyclin D3 expression was significantly decreased by NF-κB suppression in all cell lines." (PMID 24510578, 2014).
myoepithelial carcinoma (1 paper, 2019). "Key proteins in cell cycle regulation, including c-myc, p21, Cdk4, and Cyclin D3, were all recently documented as potential prognostic factors in myoepithelial carcinoma of salivary glands." (PMID 31827554, 2019).
nasopharyngeal carcinoma (1 paper, 2016). A carcinoma arising from the nasopharyngeal epithelium. "Overexpression of miR-188 inhibits cell proliferation, tumor colony formation and G1/S cell cycle transition in human nasopharyngeal carcinoma CNE cells by inhibiting CCND1, CCND3, CCNE1, CCNA2, CDK4 and CDK243." (PMID 27708404, 2016).
nodular melanoma (1 paper, 2019). "However, in this study, there was no statistically significant between the high expression levels of cyclin D3 and overall survival for nodular melanoma patients (p = 0.23)." (PMID 31198407, 2019). "But one of studies that differ from the majority included cohorts suggested that high-expression cyclin D3 is related to better OS and DFS in nodular melanoma, while the conclusion was interestingly opponent in superficial melanoma." (PMID 31198407, 2019). "Thus, cyclin D3 is not likely to act as a prognosis factor for the nodular melanoma patients and other proteins or pathways might be at work to promote nodular melanoma and play a prognostic role." (PMID 31198407, 2019).
ovarian tumors (1 paper, 2013). "Co-amplified genes were also prominent in the high-risk ovarian tumors including case OC-04 with high level CCNE1 amplification and co-amplification of CCND1, CCND3, MYC and ETV6 genes." (PMID 23289505, 2013).
pancreatic adenocarcinoma (1 paper, 2022). "Our findings are in line with a previous study in pancreatic adenocarcinoma, which found that CCND3 suppression did not result in compensatory upregulations in CCND1 expression." (PMID 35406445, 2022).
pancreatic ductal adenocarcinoma (1 paper, 2010). An infiltrating adenocarcinoma that arises from the epithelial cells of the pancreas. "The inactivation of the tumor suppressor p16 and the overexpression of cyclin D1 (CCND1) and/or cyclin D3 (CCND3) are common in pancreatic ductal adenocarcinoma (PDAC)." (PMID 20113529, 2010). "The cyclin D1 (CCND1) and cyclin D3 (CCND3) are frequently co-overexpressed in pancreatic ductal adenocarcinoma (PDAC)." (PMID 20113529, 2010).
seminoma (1 paper, 2020). A radiosensitive malignant germ cell tumor found in the testis (especially undescended), and extragonadal sites (anterior mediastinum and pineal gland). "Interestingly, CDK6 was amplified in 2.6% of seminomas, while CCND3 (CyclinD3; 1.7%) and CHEK1 (6.8%) were amplified or deleted in non-seminomas, respectively." (PMID 32418994, 2020).
sickle cell disease (1 paper, 2024). Sickle cell anemias are chronic hemolytic diseases that may induce three types of acute accidents: severe anemia, severe bacterial infections, and ischemic vasoocclusive accidents (VOA) caused by sickle-shaped red blood cells obstructing small blood vessels and capillaries. "Our data suggest that CCND3 is a possible therapeutic target in sickle cell disease." (PMID 39056767, 2024).
Splenomegaly (1 paper, 2026). Abnormal increased size of the spleen. "Upregulation of γ- and δ-globin levels in mice lacking Ccnd3 expression contributes to partial restoration of the α/β balance, with a consequent increase in hemoglobin levels, improvement of iron levels, and reduction of splenomegaly." (PMID 41892286, 2026).
squamous carcinomas (1 paper, 2006). "Interestingly, it has been suggested that cyclin D3 preferentially promotes development of squamous carcinomas and that it activates an oncogenic pathway in mammary epithelial cells that is distinct from the pathway induced by cyclin D1." (PMID 16569260, 2006).
thyroid (1 paper, 2025). "Most of the 16 thyroid-related genes, in addition to several cancer-related genes including AKT2, VEGFA, ERBB2, and CCND3, were positively correlated with TDS." (PMID 41353477, 2025).
type 1 diabetes (1 paper, 2025). "Subsequently, we performed immunofluorescence staining for cyclin D3 (a cell cycle-related protein) and GS (a Müllerian glial marker) using eyes from control mice, Ambra1-deficient mice, and STZ-induced type 1 diabetes model mice." (PMID 41001311, 2025).